LETR1 (lymphatic endothelial transcriptional regulator lncRNA 1)
Synonyms: LINC01197
Gene: Long non-coding RNA gene on chromosome 15 (95,166,065 to 95,327,129, reverse strand). Ensembl gene ENSG00000248441.
Diseases named in the same sentence as LETR1 in open-access papers:
LETR1 is named in the same sentence as 5 diseases in open-access papers, as found by Europe PMC text mining. Sharing a sentence is not in itself a finding about the gene and the disease. The quoted sentences say what the papers report.
ductal pancreatic adenocarcinoma (1 paper, 2021). "A recent study reported that viral ectopic expression of FOXO1 in ductal pancreatic adenocarcinoma cells upregulates LINC01197 (LETR1), resulting in the inhibition of cell proliferation." (PMID 33568674, 2021).
tumor (3 papers, 2019 to 2023). "Through these interactions, LETR1 controls intricated transcriptional networks to fine-tune the expression, above all, of essential proliferation- and migration-related genes, including the tumor-suppressor TF KLF4 and the semaphorin guidance molecule SEMA3C." (PMID 33568674, 2021).
LETR1 also shares sentences with these, for which no sentence is quoted: infection (1 paper); pancreatic adenocarcinoma (1); viral infection (1).